BRCA2 (BRCA2 DNA repair associated)
Diseases named in the same sentence as BRCA2 in open-access papers (continued):
Sharing a sentence is not in itself a finding about the gene and the disease.
prostate carcinoma (continued). "Male carriers are advised to undergo clinical breast exams starting at age 35 and prostate cancer screening with a digital rectal exam and prostate-specific antigen (PSA) testing starting at age 40, especially for BRCA2 carriers." (PMID 39590130, 2024). "The effectiveness of PARPi therapies for resistant prostate cancer with alterations in DNA-repair genes, in particular BRCA1 and BRCA2, has been widely tested." (PMID 39335746, 2024). "The co-deletion of BRCA2 and RB1 emerged as an independent genomic driver of castration-resistant prostate cancer (CRPC), contributing to an aggressive phenotype characterized by epithelial-to-mesenchymal transition (EMT)." (PMID 38672640, 2024). "Taken together, these findings collectively emphasize the therapeutic potential of targeting DDR pathways, especially in the context of BRCA2 and RB1 co-deletion, to combat the progression of castration-resistant prostate cancer." (PMID 38672640, 2024). "Here, we report an overview of CGP results, specifically of BRCA1 and BRCA2 HRD-repair system genes, from patients with prostate cancer analyzed in our institution, and we compare our results with those available from more recent scientific literature." (PMID 39335746, 2024). "Data regarding genomic alterations in populations of prostate cancer patients in SSA was minimal, including data on frequency of BRCA1, BRCA2 or other homologous recombination repair genes." (PMID 37368872, 2023). "It has been revealed that DDR genes alterations including BRCA2, BRCA1, CDK12, ATM, FANCD2, or RAD51C affect almost 20% of 333 primary prostate cancer." (PMID 36739400, 2023). "Similarly, we found a significantly increased risk for prostate cancer in male relatives of BRCA2 carriers (RR = 4.86; P = 0.001), but a non-significant risk in male relatives of BRCA1 carriers (RR = 2.19; P = 0.241); our finding is in agreement with previous studies." (PMID 36861435, 2023). "Several tumor types, particularly breast, ovarian, pancreatic, and prostate cancer, exhibited a strong correlation between elevated gLOH and biallelic alterations in multiple key HRR genes beyond BRCA1 and BRCA2." (PMID 38201431, 2023). "In the joint analysis of BRCA1 and BRCA2 carriers, men in the top PRSPC quartile had a prostate cancer odds ratio of 3.35 (95% CI = 2.06 to 5.42) compared with men in the lowest quartile (available online)." (PMID 34320204, 2022). "For example, most hereditary cancer panels include genes for breast, ovarian and colon cancer – and includes the five main genes for prostate cancer discussed here (BRCA1, BRCA2, CHEK2, ATM, PALB2)." (PMID 35732815, 2022). "Poly (ADP-ribose) polymerase (PARP) inhibitor (PARPi) studies in prostate cancer (PCa) have focused primarily on the homologous recombination repair (HRR) genes, specifically BRCA1 and BRCA2." (PMID 36230674, 2022). "In a large dataset of 7,707 men with advanced prostate cancer undergoing comprehensive genomic profiling (CGP) of cell-free DNA (cfDNA), 614 men harbored BRCA1 and/or BRCA2 alterations." (PMID 36185208, 2022). "It would be logical to theorise that prostate cancers with PALB2 (partner and localiser of BRCA2) alterations would respond to PARPi similarly to BRCA2, given its role in HRR." (PMID 36497408, 2022). "BRCA2 (12–18%), ATM (3–6%), CHEK2 (2–5%), and BRCA1 (< 2%) are the most commonly affected HRR genes in prostate cancer." (PMID 35159068, 2022). "As such, we decided to generate CRISPR-mediated BRCA1 or BRCA2 gene KOs in the ovarian adenocarcinoma cell line SKOV3 and the prostate carcinoma DU145 cell line." (PMID 36969741, 2022).
prostate carcinoma (continued). "We identify multiple somatic aberrations that are known to be enriched in prostate cancer, including a deletion of PTEN and a fusion transcript involving BRCA2." (PMID 33922147, 2021). "Next-generation sequencing studies have revealed that about 10% of primary tumors and 25% of metastases from prostate cancer harbor DDR defects with BRCA2 aberrations consistently described as the most common event." (PMID 30871108, 2019). "Intriguingly, we show that BRCA2-proficient castration-resistant cancer cells become resistant to paclitaxel treatment, suggesting that BRCA2 genetic reversion or high basal levels of BRCA2 in prostate cancer patients may predict resistance to taxane-based therapy." (PMID 31284411, 2019). "Of these, BRCA2, BRCA1, and ATM account for 19.3% overall and they were substantially more frequent in mCRPC compared to those in primary prostate cancers." (PMID 31357527, 2019). "BRCA2 knockdown by siRNA or shRNA in C4-2 and DU145 prostate cancer cells instead increased apoptosis induced by 6-TG or the PARP inhibitor olaparib but not by PTX." (PMID 31284411, 2019). "In prostate cancer, autoantibody frequency to PARP1/BRCA1/BRCA2 were 2.8% (3/107), 28.0% (30/107) and 4.7% (5/107), 1.9% (2/107), 0.9% (1/107) and 1.9% (2/107) were shown to have autoantibody to PARP1 and BRCA1, PARP1 and BRCA2, or BRCA1 and BRCA2." (PMID 25865228, 2015). "Promising phase I clinical data in BRCA2 carriers with a PARP inhibitor has shown antitumour activity, including resolution of bone metastases in one patient with prostate cancer." (PMID 20585617, 2010). "In a case series of 263 men in the UK diagnosed with prostate cancer at younger ages (⩽55 years), and who were not selected on the basis of either breast or prostate cancer family history, the prevalence of protein-truncating BRCA2 mutations was 2.3% (95% confidence interval (95%CI) 0.8–5.0%)." (PMID 17700570, 2007). "The proportion of aggressive prostate cancer in BRCA1 carriers was the same as in BRCA2 carriers (86.7%), which was higher than in noncarriers (61.1%) (odds ratio [OR] = 4.87; 95% confidence interval [CI] = 1.05 to 22.60; P = .043)." (PMID 41423785, 2026). "There were 5271 prostate cancer patients included with 18 (0.3%) having germline BRCA1 alterations, 139 (2.6%) with BRCA2 alterations, 49 (0.9%) with germline ATM alterations, 15 (0.3%) with germline PALB2 alterations, and 27 (0.5%) with germline CHEK2 alterations." (PMID 40361359, 2025). "The contribution of BRCA1 mutations to familial prostate cancer is not as strong as that seen for BRCA2, although BRCA1 mutations have been associated with some populations with a family history of prostate cancer." (PMID 40433050, 2025). "The study did, however, report that patients with metastatic castration-resistant prostate cancer and germline BRCA2 PVs had a worse OS compared to patients without such PVs." (PMID 37511593, 2023). "In several tumor types, particularly breast, ovarian, pancreatic, and prostate cancers, a strong correlation was observed between increased gLOH and biallelic alterations in other HR genes beyond BRCA1 and BRCA2, including BARD1, PALB2, FANCC, RAD51C, and RAD51D." (PMID 37761329, 2023). "Instead, a prostate cancer cluster region (PCCR) was identified in BRCA2 gene from c.7914 to 3′, but no PCCR was established in BRCA1." (PMID 38203374, 2023).
prostate carcinoma (continued). "For example, laboratory-developed panels may be designed for analyzing only BRCA1/BRCA2 and the other HRR genes clinically relevant in prostate cancer." (PMID 37240284, 2023). "Prospective data suggest that BRCA2 and co-occurring somatic alterations, including RB1 loss and MYC amplification, define an aggressive subtype of prostate cancer, the therapeutic implications of which are currently not well understood." (PMID 36497408, 2022). "The present estimate is unlikely to be subject to increased screening biases since prostate cancer family history was retrospectively collected, and increased screening in relatives is unlikely to have taken place before the identification of BRCA2 PVs." (PMID 35077220, 2022). "For example, in prostate cancer, PCAT-1 was proved to have a prominent inhibitory effect on the HR activity by a direct interaction with the 3′UTR of BRCA2, thus affecting subsequent post-transcriptional suppression of BRCA2." (PMID 36246624, 2022). "In a meta-analysis, the pooled relative risks (RRs) for prostate cancer were 4.35 and 1.18 for non-Ashkenazi European ancestry BRCA2 and BRCA1 GPV carriers, respectively." (PMID 35806485, 2022). "In addition, the alterations of gene expression are also considered to be related to the development of prostate cancer, such as HOXB13, BRCA1, BRCA2, as well as our protagonists HSP90 and HSP70." (PMID 36294924, 2022). "The past decade has seen several therapeutic breakthroughs for prostate cancer, including the approval of two PARP inhibitors—rucaparib and olaparib—for mCRPC patients harboring germline or somatic aberrations in DDR genes such as BRCA1 and BRCA2." (PMID 35159068, 2022). "The risks of developing prostate cancer by the age of 75 years were reportedly 21% and 27% for BRCA1 and BRCA2 GPV carriers, respectively, and the risks of developing pancreatic cancer by 75 years were reportedly 1–3% and 3–5% for BRCA1 and BRCA2 GPV carriers, respectively." (PMID 35806485, 2022). "PROREPAIR-B is an ongoing prospective study to evaluate the outcomes of patients with metastatic castrate-resistant prostate cancer with and without germline ATM/BRCA1/BRCA2/PALB2 mutations." (PMID 35732815, 2022). "The mean count of copy number alterations in prostate cancers was reported to be 3-fold higher among germline carriers of BRCA2 PSV relative to non-carriers, with gains considerably more common in the region encompassing c-MYC13." (PMID 35715489, 2022). "In advanced prostate cancer cases, the co-deletion of RB1 and BRCA2 is frequently found." (PMID 34359636, 2021). "The Advanced Prostate Cancer Consensus Conference held in 2019 supported consideration of BRCA1 and BRCA2 testing in screening, management, and informing prognosis/treatment, with germline testing recommended in patients with a tumour BRCA1, BRCA2, or ATM mutation." (PMID 33630412, 2021). "In the LNCaP prostate cancer cell line, PCAT1 knockdown led to an increased BRCA2 protein expression, while PCAT1 overexpression decreased BRCA2 protein level and impaired repair of double-strand brakes, thus sensitizing cells to PARP1 inhibitors and radiation." (PMID 33918762, 2021). "These cancers may also be relevant in investigating genes that confer lifetime risks of prostate cancer, such as BRCA1 and BRCA2." (PMID 32948129, 2020). "Moreover, aberrations of BRCA2, BRCA1, and ATM were observed in mCRPC at clearly higher frequencies than in primary prostate cancers." (PMID 31366128, 2019). "To learn about the statuses of BRCA1 and BRCA2 in prostate cancer and non-cancerous cells, we assessed their protein levels." (PMID 30012171, 2018).
prostate carcinoma (continued). "A 2008 study suggested a trend of increased expression of CD117 during prostate cancer metastasis to the bone; a follow-up study in 2015 by the same lab found a novel pathway linking CD117 expression with BRCA2 downregulation that induced bone metastasis of prostate cancer." (PMID 29518044, 2018). "PSA > 3.0 was found to have a 48% positive predictive value for prostate cancer in the BRCA2 population compared to 24% in controls who were not carriers of BRCA1/2 mutations." (PMID 28946846, 2017). "In contrast to results shown in prostate cancer, no radiosensitization was observed in the BRCA2 germline mutant tumor in response to treatment with AZD-2281." (PMID 28033382, 2016). "Although germline mutations and LOH in BRCA1 and BRCA2 genes have been detected in mutation carriers, no data currently exist concerning the role of RAD51 in sporadic prostate cancer." (PMID 26433958, 2015). "Although the contribution of the homologous recombination mediators BRCA1 and BRCA2 to prostate cancer has been previously investigated, this is the first study to address the importance of RAD51 genetics in the occurrence of sporadic prostate cancer." (PMID 26433958, 2015). "There is a recent report that BRCA2 carriers with prostate cancer have poorer survival than noncarrier prostate cancer patients." (PMID 18577985, 2008). "Indeed, in UKB European cohort, we found that 2.9% (48/1641) of all aggressive prostate cancer cases carried a BRCA2 or ATM QV compared to 0.9% (114/12,936) of non-aggressive prostate cancer cases (PFET = 1.46 × 10−10)." (PMID 39971927, 2025). "Several other cancer types were detected in the 1st–3rd degree relatives of almost all BRCA1, BRCA2 and PALB2 carriers, the most common ones being stomach (in 10 families), lung (9 families), colorectal (6 families), pancreatic (6 families) and prostate cancer (5 families)." (PMID 40009290, 2025). "Consistently with previous reports, the frequency of alterations in AR and HRR genes including BRCA2 and ATM was enriched in mCRPC compared with mCSPC, suggesting that alterations in AR and HRR genes promote treatment resistance to initial ADT-based therapy in prostate cancer." (PMID 39516321, 2024). "Additionally, higher risks of pancreatic and prostate cancers were noted in male relatives of BRCA2 carriers than non-carriers (RR = 4.34, P = 0.001 and RR = 4.86, P = 0.001, respectively)." (PMID 36861435, 2023). "Therefore, patients with prostate cancer and pathogenic variants of BRCA1/BRCA2 or ATM are not appropriate candidates for active surveillance, even if other clinical and pathological features are acceptable." (PMID 37174127, 2023). "Recently, a large family-based study suggested that BRCA2 P/LPVs are associated with a statistically significant risk for stomach cancer, while associations of BRCA1 P/LPVs carriers with prostate cancer or cutaneous melanoma could not be confirmed." (PMID 36230512, 2022). "The lower odds ratios for the breast and prostate cancer PRS in male BRCA1 and BRCA2 carriers, compared with the general population, may reflect a general attenuation of the effect sizes of common variants on genetic risk in the presence of a pathogenic variant in a high-risk gene." (PMID 34320204, 2022). "However, studies conducted in prostate cancer patients have revealed that 30% of patients harboring a germline mutation in a DDR gene and 15% of those who carry a BRCA2 mutation do not have a relative affected by cancer." (PMID 30871108, 2019). "BRCA2 mutation involves a lifetime risk of developing PC ranging from 30-40%, while BRCA1 mutation carriers present a 3–8% lifetime risk with a modestly elevated incidence of early onset prostate cancer but no increased risk in older men." (PMID 27819754, 2017).
prostate carcinoma (continued). "Future studies should also address whether current surgical and non-surgical treatments improve survival from prostate cancer among BRCA2 carriers." (PMID 18577985, 2008). "However, the majority of studies that have investigated the role of BRCA2 mutations in hereditary prostate cancer (HPC) families, which usually include men diagnosed with prostate cancer at younger ages, have reported no disease-associated mutations." (PMID 17700570, 2007). "The kind of mutated genes in PSs and MSs was similar, such as tumor suppressor gene BRCA2 and RB1, but the alteration frequency had typically declined in PSs, which might suggest that genes in chromosome 13 play an important role in tumor metastasis as reported in prostate cancer." (PMID 33014052, 2020). "Patients with prostate cancer who did not respond to prostate‐specific membrane antigen‐targeted alpha‐radiation therapy had their BRCA1 and BRCA2 genes removed, and multiple BRCA1 variations had been found." (PMID 37808268, 2023). "A total of 2,932 men with no history of prostate cancer were categorized into 919 germline BRCA1 carriers, 902 germline BRCA2 carriers, 479 germline BRCA2 non-carriers and 709 germline BRCA1 non-carriers." (PMID 34884434, 2021). "Family history of prostate cancer was seen in 15.4% of PALB2 carriers but in only 1.7% of BRCA1 carriers (p-value = 0.001); there was no significant different between PALB2 and BRCA2 carriers (p-value = 0.594)." (PMID 34439348, 2021). "Evidence from prostate cancer and other tumor types has shown efficacy of PARP inhibitors for tumors with BRCA1 or BRCA2 alterations, but without complete responses." (PMID 26258074, 2015). "This study analyzed the tumor features and outcomes of 2,019 patients with prostate cancer (18 BRCA1 carriers, 61 BRCA2 carriers, and 1,940 non-carriers)." (PMID 25047061, 2014). "However, in Ashkenazi men with prostate cancer, the prevalence of BRCA1 and/or BRCA2 is not well defined." (PMID 36612302, 2023). "Here we present a case report of a patient with prostate cancer in whom rebiopsy and WGS at the point of disease progression had a significant and ongoing clinical impact because of the identification of a tumoral BRCA2 deletion not present in the initial biopsy." (PMID 28487881, 2017).